MYC (MYC proto-oncogene, bHLH transcription factor)
Diseases named in the same sentence as MYC in open-access papers (continued):
Sharing a sentence is not in itself a finding about the gene and the disease.
tumor (continued). "In the light of an elusive pharmacologic MYC inhibitor, our results highlight the importance of DNA methylation in MYC-driven tumor maintenance, and reveal the potential of specific components of the DNA methylating machinery for targeted therapeutic strategies." (PMID 29100357, 2017). "Since transcriptional upregulation of MYC expression can trigger and propagate tumour pathogenesis, we focused the next part of this review on the mechanisms orchestrating expression of MYC under normal circumstances and reflect on their disarray in the context of cancer." (PMID 28398229, 2017). "Glutamine-deprivation induced apoptosis of tumor cells and MYC-transformed cells can be rescued by addition of exogenous alpha-ketoglutarate (α-KG) to the cells, suggesting that the anaplerotic flux of glutamine into the Krebs cycle is a critical survival mechanism." (PMID 28443281, 2017). "Tumor cells start the de novo expression of MYC, and its redundant quantity enables the constitutive activity of already induced oncogenic pathways, in a similar way to how its expression in a subset of normal B cells enhances the already established gene expression profile." (PMID 28375188, 2017). "Importantly, in order to adapt to the tumor microenvironment, MYC also joins the metabolic reprogramming, which is essential for cancer cells." (PMID 28749413, 2017). "Besides, MYC overexpression was related to tumor size of more than 2 cm, high histologic grade, lymph node metastasis, negative ER status, negative PR status, positive Ki67 expression." (PMID 29212204, 2017). "Finally, the induction of p27 by cytokines like IFN-γ and TGF-β or by differentiation-, cell density- and adhesion-signals has been shown to inhibit growth of MYC-driven tumor cells in different systems." (PMID 28665315, 2017). "Tumor cells typically exist in a micro-environment that is hypoxic, and express high levels of MYC." (PMID 28362357, 2017). "However, since inhibition of mTOR has effects on nutrient uptake by tumor cells and alters their metabolism, targeting mTOR signaling to regulate MYC protein is a potential approach." (PMID 28362357, 2017). "MYC overexpression in tumor cells, regardless of the underlying mechanism, influences many different signaling pathways, all resulting in a more aggressive clinical course of the disease." (PMID 28375188, 2017). "Therefore, in this tumour setting, constitutive c-MYC expression circumvents the requirement for EBV to drive proliferation, but it does place an imperative on EBV to block cellular apoptosis during oncogenesis." (PMID 29137176, 2017). "Here we discuss evidence of aberrant signaling contributing to MYC transcriptional upregulation and/or enhanced MYC protein stability in a variety of tumor types, including chronic myeloid Leukemia (CML), T-cell acute lymphoblastic leukemia (T-ALL), breast, colorectal, and liver cancers." (PMID 28587062, 2017). "The expression of MPC1 was negatively correlated with the MYC oncogene and positively correlated with the colon tumor suppressor APC also supported this hypothesis." (PMID 27911865, 2017). "In cancer, much focus has been placed on the role of GSK-3β in tumor progression and modulation of oncogenes (beta-catenin, cyclin D1, and c-MYC), cell cycle regulators (e.g., p27Kip1), and mediators of epithelial-mesenchymal transition (e.g., snail) by GSK-3β have been described." (PMID 29383130, 2017). "None of the patients with a pRCC type 1 and the favorable (negative or strong) MYC staining patterns died from tumor-related causes." (PMID 29180625, 2017). "More recently, it was shown to regulate tumor metabolism via MYC activation." (PMID 28704924, 2017). "Significant tumor heterogeneity might exist between patients, and therefore a more personalized assessment of MYC dependence may be needed." (PMID 28362357, 2017).
tumor (continued). "This putative negative correlation between the expression of MYC/MYCL/MYCN and HIF2A is supported by data retrieved from the databank of a published expression analysis of 81 SCLC tumor specimens showing that tumors with high pan-MYC expression generally express low levels of HIF2A (PMID: 26168399)." (PMID 28430666, 2017). "In support of this hypothesis, reversal of the MYC-driven miRNA signature results into smaller tumor formation in mice." (PMID 28217689, 2017). "Furthermore depletion of MYC using shRNA leads to proliferative arrest in multiple tumor cell lines." (PMID 29163823, 2017). "We observed seven let-7 family members (let-7a, let-7b, let-7c, let-7d, let-7e, let-7f, and let-7 g) to be downregulated in eBL tumor cells compared to GC B-cells consistent with their functional role in the genesis and maintenance of eBL tumor cells in the presence of MYC deregulation." (PMID 29132323, 2017). "Moreover, MYC gene amplification or increased MYC activity is often correlated with aggressive tumor phenotypes and poor outcomes in many cancers." (PMID 28333115, 2017). "One speculative hypothesis is that a functional equivalent of Msn2/4 in mammalian cancer is MYC, which similarly targets all glycolytic enzymes and fosters tumor growth." (PMID 28949295, 2017). "Another mechanism could be related to the cellular context and the fact that certain cells of tumor origin have a certain set of collaborating genetic and epigenetic alterations that either promote or inhibit tumor cell death upon MYC gene depletion." (PMID 28333115, 2017). "We generated cell lines from VM and VIM tumours to assess their dependency on MYC expression." (PMID 28593993, 2017). "Tumor cells could attempt escape from the synthetic lethality with MYC by downregulating AMPK activity, which event, however, would endanger tumor cells' lives due to loss of bioenergetic homeostasis." (PMID 28443281, 2017). "Hence, we conclude that DNMT3B contributes to tumor maintenance of MYC-driven T-ALL through its effects on DNA methylation, and that loss of DNMT3B causes the reactivation of gene transcription through reversing CpG island methylation." (PMID 29100357, 2017). "As MYC is such a ubiquitous oncogenic driver, we presume that heterogeneity within the MYC-low tumours or alternative mechanisms for activation of the MYC-driven transcriptional program are more likely reasons for this difference, rather than MYC not being a DNA-binding factor driving malignancy." (PMID 28592290, 2017). "For instance, elevation of MYC will not only enhance cellular overgrowth and tissue hyperplasia (by binding promoters that are active in proliferating tumour cells), but will also upregulate expression of weakly expressed cancer-promoting targets to accelerate tumour progression." (PMID 28398229, 2017). "These miRNAs have been shown to repress MYC controlling proliferation and tumor development." (PMID 29132323, 2017). "However, via K63‐mediated ubiquitination, HUWE1 is required for the transactivation function of MYC and tumour cell proliferation." (PMID 28003334, 2017). "Phosphorylation of MYC at T58 and S62 was consistently present in all tumor cells." (PMID 28152508, 2017). "c-MYC overexpression in MDA-MB-231 cells has previously been shown to increase tumor volumes in vivo and may have contributed to faster tumor growth as compared to MCF7 tumors." (PMID 28147343, 2017). "Finally, we assessed the ability of MYC-2983 cells to form tumours in vivo and their in vivo growth dependence on MYC expression." (PMID 28593993, 2017).
tumor (continued). "Another example of the crosstalk between c-MYC and growth factors are double transgenic mice expressing epidermal growth factor (EGF) and c-MYC, in which exacerbated tumor progression and mortality led to the occurrence of HCC in 100% of the mice after approximately 12–18 weeks." (PMID 28422055, 2017). "Considering multiple signaling pathways converge on MYC it is not surprising that overexpression is frequently observed in multiple tumor types where elevated MYC levels are associated with malignant transformation and tumor proliferation." (PMID 29163823, 2017). "MYC overexpressing tumor cells can utilize glutamine as energy source." (PMID 28430666, 2017). "In addition to the elimination of stromal cells, which recurred in all the samples analysed, we were also able to observe Cas3-positive tumour cells close to or surrounded by high c-MYC expressing cells." (PMID 28974715, 2017). "MYC has been shown to directly regulate the expression of the tumor cell surface immune checkpoint protein cluster of differentiation 47 (CD47) and programmed death-ligand 1 (PD-L1), which mediate “don’t eat me” and “don’t find me” signals, respectively, following MYC binding to their promoters." (PMID 28757546, 2017). "We have shown in a previous Smurf2T/T related publication that MYC expression is elevated in spleen and liver tissue for Smurf2T/T mice started at two months of age and also highly expressed in the eventual formation of the tumor." (PMID 28107482, 2017). "Interestingly, in addition to observing super-enhancers targeting oncogenes, such as c-MYC, we also observed super-enhancers that were either near tumor suppressor genes or connected to tumor suppressor genes through chromatin interactions." (PMID 28526829, 2017). "Therefore, we analyzed the combination of histomorphology and MYC staining patterns using a multivariate model and adjusted this model to the patient’s age at surgery, pathological tumor stage and presence of lymph node invasion." (PMID 29180625, 2017). "Going forward, quantification of MYC protein levels through tumor proteomics and a more precise definition of MYC activation and/or the MYC transcriptional program may facilitate a better understanding of MYC deregulation in oncogenesis." (PMID 28587062, 2017). "Finally, we describe how the MYC/CDK2/p27/SKP2 axis impacts on tumor development and discuss possible ways to interfere therapeutically with this system to improve cancer treatment." (PMID 28665315, 2017). "None of the patients with pRCC type 1 tumors that displayed negative or strong MYC staining patterns died of tumor-related causes during the complete observation period." (PMID 29180625, 2017). "This increase in MYC protein was also observed in Huwe1‐deficient Vil Apc Huwe1 tumours compared to controls and was independent of transcriptional effects." (PMID 28003334, 2017). "The ability of MYC to act both locally and globally on chromatin may be responsible for its wide-ranging effects on the biology of stem and tumor cells." (PMID 28505071, 2017).
tumor (continued). "In this latter image, the arrow indicates a cluster of apoptotic cells showing a c-MYC level comparable to that of other tumour cells in the field; it is however “embraced” by higher c-MYC-expressing cells, and this may cause its elimination." (PMID 28974715, 2017). "Moreover, transcriptome wide Pearson correlations revealed that MYC tumours more closely resemble TCGA KIRP tumours verified to be Type 2 pRCC." (PMID 28593993, 2017). "Recent studies have demonstrated that blocking MYC function may be sufficient to stop tumor growth and induce tumor regression in the well-characterized LSL KRAS G12D mouse models of NSCLC and PDAC." (PMID 28152508, 2017). "Two recent studies demonstrated that MYC played different roles in tumor and normal tissues." (PMID 29340052, 2017). "As MYC is a critical modulator of intestinal tumourigenic, we hypothesised that the modulation of MYC stability may be a key tumour‐suppressive function of HUWE1 within the gut." (PMID 28003334, 2017). "Moreover, c-MYC expression is elevated in tumor-cell fractions that have survived platinum-based chemotherapy in vivo." (PMID 28590415, 2017). "Altogether, the evidence that co-expression of the HBx and c-MYC transgenes accelerated HCC development in transgenic mice clearly establishes this viral transactivator as a tumor promoter, and as a cooperating partner of the c-MYC oncogene in liver cell transformation." (PMID 28422055, 2017). "We next examined whether human ccRCC tumours with similar genomic characteristics (VHL inactivation; VHL inactivation and MYC activation; and VHL inactivation, CDKN2A loss and MYC activation) have similar outcomes as those seen in our mouse models." (PMID 28593993, 2017). "Due to the pleiotropic effect of MYC expression in oncogenic transformation, MYC is an ideal target for pharmacological intervention, and targeting MYC could have broad-range anti-tumor activity." (PMID 28704924, 2017). "MYC protein levels are increased and drive increased tumour proliferation but are not the primary cause of the increased tumour initiation." (PMID 28003334, 2017). "These complex dynamics go well beyond the genetic structure of the participating cells, and it is conceivable that new findings will come from the analysis of MYC-mediated CC between different cell species, such as cancer and stromal cells composing the tumour microenvironment." (PMID 28420161, 2017). "None of the patients with pRCC type 1 tumors and favorable MYC staining patterns died from tumor-related causes." (PMID 29180625, 2017). "Here we show stereotypical patterns of MYC-mediated cell competition in human cancers: MYC-upregulating cells and apoptotic cells were indeed repeatedly found at the tumour-stroma interface and within the tumour parenchyma." (PMID 28974715, 2017). "The MYC regulates the expression of two immune checkpoint proteins on the tumor cell surface, the innate immune regulator, CD47 (Cluster of Differentiation 47) and the adaptive immune checkpoint, PD-L1 (programmed death-ligand 1), thereby initiates and maintains the tumorigenesis." (PMID 28278192, 2017). "Also IBC tumor samples showed amplifications in the following: MYC (8/32; 25%), CCND1 (7/32; 22%), ErbB2 (5/32; 16%), MCL1 (6/32; 19%), and FGFR1 (3/32; 9%)." (PMID 28271309, 2017). "Glucose metabolism and oxidative phosphorylation, along with the metabolism of nucleotides, fatty acids, and glutamine, all seem to have important roles based on the conditions in the tumor micro-environment, with hypoxia-inducible genes and MYC target genes both being key players." (PMID 28362357, 2017). "Let-7 tumor suppressor activity was found to exert an effect upon two of the most important oncogenic genes, RAS (encodes proteins that are involved in kinase signaling pathways) and c-MYC (v-myc avian myelocytomatosis viral oncogene homolog)." (PMID 27187371, 2016).
tumor (continued). "Further studies need to determine whether MYC plays a different tumorigenic role in these various models and whether they all result in similar tumor behavior." (PMID 27775567, 2016). "However, it is predicted that the effects of these inhibitors would be restricted to tumours where c-MYC transcription is dependent on BRD4." (PMID 26729287, 2016). "Isolation of novel coding and non-coding MYC targets with strong oncogenic activities could be done by cDNA expression cloning using MYC-dependent tumor cells as a source for RNA isolation." (PMID 27313991, 2016). "This new MXD1 function would be important to curb MYC activity in tumor cells." (PMID 27588501, 2016). "Due to the pleiotropic MYC effect leading to the development of multiple different tumor forms, one could postulate that simultaneous perturbation of multiple targets suffices to convert a normal cell into a cancer cell displaying a MYC-transformed phenotype." (PMID 27313991, 2016). "Furthermore, combinatorial expression of ADA3 and c-MYC showed significant correlation with tumor grade, mitosis, pleomorphism, Nottingham Prognostic Index (NPI), ER/PR status, Ki67 and p27 expression." (PMID 27852327, 2016). "This suggests that elevated MYC expression in the NHPrE1/AR tissue recombinants may result from signals from other cellular components, such as immune cells, of the tumor microenvironment." (PMID 27611945, 2016). "The MYC pathway activity was assessed in each tumour as the mean expression of MYC target genes." (PMID 27090007, 2016). "Additionally, MYC is not only required for tumor initiation, but also necessary for tumor maintenance." (PMID 27775567, 2016). "Further studies may show that the altered regulation of a tumor-specific set of genes is important for tumor development and could use this new information to identify new targets for treating MYC-driven tumors." (PMID 27460974, 2016). "Similarly, BPTF knockdown in PK9 and MIA Paca-2 cells led to reduced proliferation, indicating that tumour types with different c-MYC dependency require BPTF to sustain proliferation." (PMID 26729287, 2016). "Tumor derived cell lines were generated from the MYC-, RAS-, and BCR-ABL-induced ALLs." (PMID 27095570, 2016). "BPTF is overexpressed in tumours together with c-MYC and, in some cases, N-MYC and L-MYC." (PMID 26729287, 2016). "MYC positive tumor cells by IHC ranged from 0% to 80% (mean ± SD, 28.3±25.3%)." (PMID 27527850, 2016). "Notably, these studies have revealed that the effect of JQ1 on tumor regression appears to be specifically mediated by downregulation of MYC itself, its downstream targets, and inflammatory signals." (PMID 27081479, 2016). "In addition, two negative regulators of MYC, mir34b and mir34c21, 22, 23, were down-regulated in O1 tumours and their transcription start sites, lying within the mir34b/c CpG island, were hypermethylated in both POLA and TCGA datasets." (PMID 27090007, 2016). "A few well-studied oncogenes, such as MYC, have weak evidence for tumor suppression." (PMID 26590405, 2016). "Because every cancer starts with a different pattern of gene expression and a different level of MYC, this may result in each tumor having a distinct transcription profile." (PMID 27460973, 2016). "However, 32% of O1 tumours didn’t harbour any of these four alterations despite showing a high MYC activity." (PMID 27090007, 2016). "Interestingly there is also an inhibitory influence of BASP1 on the oncogene MYC implicating BASP1 as a tumour suppressor." (PMID 26934553, 2016).